NRP2 (neuropilin 2)
Diseases named in the same sentence as NRP2 in open-access papers (continued):
Sharing a sentence is not in itself a finding about the gene and the disease.
tumor (continued). "Monoclonal antibodies targeting the VEGF-C binding domain of NRP2 have been developed and were able to decrease the number of tumour-associated lymphatic vessels and metastasis in animal xenograft experiments." (PMID 32708258, 2020). "NRP2 is a member of the membrane-associated neuropilin family and has been reported to be expressed during macrophage differentiation and facilitated tumor growth." (PMID 32695477, 2020). "In this context, further studies using immunocompetent mice will additionally allow to address the role of NRP2 and its siRNA-mediated knockdown in tumor associated immune cells." (PMID 31664117, 2019). "Similar to OPN, the expression pattern of NRP2 was previously reported to be significantly associated with pathological stage and tumor grade in a BCa cohort, suggesting a prominent role of NRP2 in BCa progression." (PMID 32038994, 2019). "This is in part due to the fact that NRP2 is implicated in signaling pathways commonly hijacked by tumor cells." (PMID 32038994, 2019). "NRP2 associates with a mesenchymal-like phenotype in vitro and accordingly, NRP2 correlates with a higher tumor grade in vivo indicating less differentiation." (PMID 26573807, 2015). "NRP2 has recently been implicated in tumor angiogenesis, growth, and metastasis of many other cancers." (PMID 25890345, 2015). "Overexpression of NRP2 is shown to enhance growth, correlate with invasion and is associated with poor prognosis in various tumor types, especially those of epithelial origin." (PMID 26030152, 2015). "Tumor VEGF is sensitive to the association rate for NRP2 and VEGF165, kon,V165,N2 (varies 22% for the range of parameter values examined), and we set this value to be 106 M-1 s-1, which is in the range of available experimental data (squares and triangles)." (PMID 22104283, 2011). "Recent functional studies by Caunt and colleagues have shown that blocking NRP-2 in a preclinical lung metastasis model prevented tumor metastasis by blocking the formation of tumor-associated lymphatics." (PMID 22028766, 2011). "Neuropilin-1 and NRP2 are expressed in a wide variety of human tumour cell lines and implicated in the survival, migration, and invasion of tumour cells." (PMID 20087344, 2010). "Likewise, simultaneous depletion of both endothelial NRP1 and NRP2 resulted in an equivalent loss of colocalized phosphorylated-VEGFR-2Y1175 expression from tumor vessels." (PMID 36970722, 2022). "NRP2 was reported to regulate efferocytosis by tumor‐associated macrophages, but whether it has a similar role in AM is unknown." (PMID 34861108, 2022). "Nrp2 is shown to be associated with tumor progression in vivo and poor prognosis in CRC patients." (PMID 35158941, 2022). "Importantly, depletion of NRP2 in PCa cells when combined with chemotherapeutic stress caused tumor cell death, leading to a significant reduction of growth of metastatic PCa in bone." (PMID 33990538, 2021). "The neuropilins NRP1 and NRP2 are multifunctional glycoproteins that have been implicated in several cancer-related processes including cell survival, migration, and invasion in various tumor types." (PMID 34239847, 2021). "This pathway links the loss of tumor suppressor and induction of NRP2 transcription." (PMID 30871059, 2019). "The involvement of NRP2 in tumour initiation suggests that its function may be linked to specific stem cell factors." (PMID 23436775, 2013). "Nrp2 expression by tumor cells and lymphatic endothelial cells has been linked to metastasis." (PMID 22948112, 2012). "Nevertheless, NCAM1, NRCAM, SLIT2, ALCAM, NRP1, and NRP2 also showed mild expression in Stage 4 tumor cells (primarily in cluster cIV)." (PMID 40448172, 2025). "A subsequent investigation into the comparison between the NRP isoforms for the expression levels between the SKCM cells of the TP and normal clusters highlights that NRP2 is notably increased in the presence of tumour compared to NRP1." (PMID 40134439, 2025).
tumor (continued). "Overexpression of miR-331-3p suppresses epithelial–mesenchymal transition (EMT) markers and reduced NRP-2 protein levels, confirming its tumor-suppressive role in this context." (PMID 40430075, 2025). "Previous studies have demonstrated increased NRP2 expression in various cancer types, such as lung, colorectal, pancreatic and other tumours." (PMID 39676743, 2025). "The expression levels of immune checkpoints, including BTLA, VTCN1, CD276, PDCD1, CD160, NRP2, and CD200, as well as the tumor-associated fibroblast marker FAP, were found to be higher in the high-risk group." (PMID 40364849, 2025). "One of these ligands, SEMA3F exhibits well-documented tumor-suppressive activities mediated through NRP2 and plexinA1 (PLXNA1)." (PMID 41391772, 2025). "This is interesting as in a different PanNET study regarding NRP2, it was found that NRP2 protein is expressed in circulating tumor cells sampled from NET patients." (PMID 40522948, 2025). "Empirical evidence indicates that elevated expression levels of NRP-2 correlate with increased anti-apoptotic mechanisms and enhanced metastatic potential of tumor cells." (PMID 40430075, 2025). "These patterns were validated across multiple datasets, with significantly elevated transcript levels of NRP1 and NRP2 in tumour samples compared to healthy tissues (p<0.001)." (PMID 40134439, 2025). "Preliminary studies reveal that NRP-1 and NRP-2 inhibitors can efficiently limit angiogenesis and reduce the tumor’s potential to metastasize, making them promising therapeutic targets." (PMID 40430075, 2025). "NRP2 maintains the tumor-initiating cells by stimulating α6β1 integrin; this interaction leads to the FAK/Ras pathway, leading to the activation of GL11." (PMID 40277760, 2025). "Expression of Nrp-1 and/or Nrp-2 has been found in different cell types, such as endothelial cells, neurons, pancreatic islet cells, hepatocytes, and tumor cells." (PMID 40430075, 2025). "Collectively, the Nrp2/α6β1 integrin axis drives tumor initiation and stem cell-like properties in cancer cells." (PMID 38592275, 2024). "Although NRP1 and NRP2 also affect myoepithelial cell tumor suppressor function, cells presence and integrity are disturbed, clearly disrupting the basal membrane structure." (PMID 39138514, 2024). "In addition, Nrp2 has been detected in interstitial macrophages and bronchial macrophages of the lung, as well as peritoneal macrophages, intravascular macrophages, microglia (brain resident tissue macrophages), macrophage-derived osteoclasts, and tumor-associated macrophages (TAMs)." (PMID 38592275, 2024). "In this context, our lab has pioneered efforts demonstrating that vascular endothelial growth factor (VEGF) signaling via neuropilin-2 (NRP2) in tumor cells sustains CSC properties." (PMID 39352757, 2024). "Single dose or conventional fractionated radiotherapy combined with VEGF/NRP2 inhibition delays tumor growth." (PMID 39352757, 2024). "The possibility exists, however, that radiotherapy induces the surface expression of NRP2 in some cells based on the reports that NRP2 can localize in the cytoplasm in some tumor cells and that its trafficking can be regulated by external stimuli." (PMID 39352757, 2024). "After sorting a PDX based on NRP2 surface expression, we observed that the NRP2lo population of tumor cells was significantly more sensitive to radiotherapy compared with the NRP2hi population." (PMID 39352757, 2024). "Within the tumor microenvironment, Nrp2 in endothelial cells promotes lymphangiogenesis by activating the integrin-α9β1/FAK/Erk pathway-independent VEGF-C/VEGFR3 signaling." (PMID 38592275, 2024). "The interaction of Nrp2 with integrins on cancer cells and endothelial cells promotes both tumor progression and metastasis." (PMID 38592275, 2024).
tumor (continued). "Selective depletion of Nrp2 on endothelial cells (Nrp1/2flflPDGFb.iCreER) inhibited primary tumor growth, as well as metastasis and secondary site angiogenesis by inducing the rapid transport and degradation of VEGFR2 to Rab7+ endosomes." (PMID 38592275, 2024). "The tumors treated with aNRP2-28 had a significant reduction in the percentage of cells positive for Ki-67 and fewer mitotic cells, indicating that the VEGF/NRP2 function blocking antibody also limits tumor proliferation after radiotherapy." (PMID 39352757, 2024). "In tumor blood vessels, two key molecules, neuropilin-1 (NRP-1) and neuropolin-2 (NRP-2), can regulate the vascular permeability of tumor tissue and enhance permeability through the interaction between the C-end rule (CendR) motif and neuromycin." (PMID 39518096, 2024). "Based on the TCGA database, we found that CCND1 and NRP2 mRNA expression was significantly increased in the HCC compared with adjacent non-tumor." (PMID 37928273, 2023). "The selected targets were patient-specific, as the analysis of another individual’s HPV+ OPSCC, showed that although some interactions, such as VEGFA/NRP1 and VEGFA/GPC1 were present, the most active L-Rs in the tumor were VEGFA/NRP2 and EGFR-related pathways." (PMID 37704757, 2023). "VEGFs have their own specific receptors (VEGFRs) but can also bind to NRP-1 and NRP-2 and have a well-established role in tumour growth by promoting neovascularisation, which is essential for the survival of the growing tumour mass." (PMID 37685898, 2023). "Another miRNA, miR-486-5p, has been shown in vivo to decrease tumor formation and lymphangiogenesis by targeting NRP-2 in CRC." (PMID 35052853, 2022). "Among these genes, NRP2 plays a critical regulatory role in the progression, drug resistance, and immune response of a variety of tumours, as presented in the discussion." (PMID 36172369, 2022). "To study the tumor cell-intrinsic function of Nrp2, we applied CRISPR-Cas9 genome editing to establish Nrp2-depleted (Nrp2−/−) mouse CRC organoids." (PMID 35158941, 2022). "Collectively, the data demonstrate a key role for Nrp2 in maintaining the aggressive phenotype and survival of tumor-derived CRC organoids." (PMID 35158941, 2022). "The change from the epithelial to the mesenchymal phenotype is thought to prepare the way for a more aggressive kind of neoplasia, and tumors that express NRP-2 have a greater probability of becoming metastatic." (PMID 35052853, 2022). "And the average diameters of NRP2-knockdown tumor spheres were obviously less than that of control tumor spheres." (PMID 34826008, 2022). "We next examined the impact of NRP2 isoforms on the ability of macrophages to phagocytose and process tumor cells." (PMID 35651620, 2022). "Our results highlight the importance of targeting both NRP1 and NRP2 to modulate tumor angiogenesis." (PMID 36970722, 2022). "Further differential and pathway analysis revealed remodeling of endothelial cells in AML, including high expression of C-C Motif Chemokine Ligand 21 (CCL21), TBX1 and NRP2 specifically observed in tumor LECs." (PMID 36028490, 2022). "The expression of SEMA3F was higher in healthy mucosa than in the tumor (p = 0.015) and, in contrast, the expression of NRP2 was higher in the tumor than in healthy mucosa (p = 0.001)." (PMID 35565388, 2022). "GLI1 can induce polycomb complex protein BMI-1, a stem cell regulator, which further increases NRP2 and α6β1 integrins activity, thereby accelerating tumor initiation." (PMID 35805056, 2022). "Until now, multiple studies had recognized the importance of VEGF/NRP2 signaling to the behavior of tumor initiation and resistance to therapies." (PMID 34826008, 2022). "Subcutaneous implantation of control and Nrp2−/− organoids into mice resulted in tumor formation in all groups." (PMID 35158941, 2022).
tumor (continued). "Overexpression of miR-486-5p inhibited tumor formation and lymphangiogenesis in nude mice, but overexpression of neuropilin-2 reversed this effect in the same animals." (PMID 35052853, 2022). "When challenged by 5-FU, we found that downregulation of NRP2 eradicated the protection of CAFs on tumor cells against cytotoxic agents." (PMID 34826008, 2022). "NRP1/NRP2 knockout tumor vasculature was found to express significantly less VEGFR-2 than either NRP1 or NRP2 knockout tumors, in addition to reduced phosphorylated VEGFR-2 expression." (PMID 36970722, 2022). "Genetic ablation of NRP2 in TAMs impaired clearance of apoptotic tumor cells, resulting in secondary necrosis and subsequent inflammation within tumors leading to increased CD8+ T cell and NK cell recruitment and delayed tumor growth." (PMID 35651620, 2022). "We demonstrate that NRP2 isoform expression regulates macrophage cytokine production, phagocytosis/lysosomal processing, and the ability to promote tumor cell migration in vitro." (PMID 35651620, 2022). "Although the role of Nrp2 is well established in lymphangiogenesis, the tumor cell-intrinsic role of Nrp2 remains elusive." (PMID 35158941, 2022). "Nrp-1 and Nrp-2 have been shown to be expressed on DCs, macrophages, and T-cell subpopulations and mainly exert pro-tumor effects." (PMID 35155237, 2022). "To study the tumor cell-intrinsic role of Nrp2 in the aggressive form of CRC, we aimed to generate a CRC model closely resembling the clinical correlate, EMT-high/stroma-rich CMS4 subtype." (PMID 35158941, 2022). "NRP2, which encodes the neuropilin-2 receptor that is repressed by hypoxia and regulates both VEGF and SEMA3F activity to induce tumor angiogenesis, also exhibited DGE with two DE transcripts and one transcript with changing proportions." (PMID 35562897, 2022). "Nrp1 is essential for immune response and identified as the co-receptor of VEGF to mediate angiogenesis, and Nrp2 exerts a significant role in VEGF-C/D/VEGFR-3-mediated tumor lymphangiogenesis and lymphatic metastasis." (PMID 35155237, 2022). "GLI Family Zinc Finger 1 (GLI1)-mediated signaling and VEGF receptor neuropilin (NRP2) signaling form an autocrine loop to continuously promote tumor initiation in TNBC." (PMID 35805056, 2022). "Immunohistochemistry on subcutaneous tumor tissue sections showed an increased IR expression on the cell membrane of Nrp2−/− tumors, as was observed in the organoids." (PMID 35158941, 2022). "The neuropilin (NRP) family is comprised of two genes, neuropilin-1 (NRP-1) and neuropilin-2 (NRP-2), and participate in a variety of signaling pathways that contribute to the cytoskeletal structure, angiogenesis, and tumor development." (PMID 35052853, 2022). "Nrp2 promotes tumor lymphangiogenesis through the integrin α9β1/FAK/Erk pathway rather than the VEGF-C/VEGFR3 signaling pathway." (PMID 36407100, 2022). "Following this regimen, we observed a similarly severe impediment to tumor growth and angiogenesis following the combined loss of endothelial NRP1 and NRP2." (PMID 36970722, 2022). "Acute, endothelial-specific depletion of NRP2 impaired tumor development and vascularization approximately 2-fold, revealing a novel, effective therapeutic strategy against cancerous growth." (PMID 36970722, 2022). "Surprisingly in the mice where the myeloid cells were depleted of NRP2, we observed decreased tumor burden in the tibia along with increased bone rescue, which contradicts our initial assumptions." (PMID 33990538, 2021). "By contrast, NRP2 depletion in the tumor cells reduced bone destruction, indicating an inhibition of growth of PCa cells in bone." (PMID 33990538, 2021). "The results from these in vivo studies revealed that depletion of NRP2 from osteoclasts significantly decreases tumor burden." (PMID 33990538, 2021). "The bone mass recovery was more profound in the combination group which had NRP2 depletion in tumor cells and received docetaxel." (PMID 33990538, 2021).
tumor (continued). "Depletion of NRP2 in tumor cells was confirmed by mRNA analysis of tumor cells isolated from the mouse bones." (PMID 33990538, 2021). "Even with increased osteoclasts, the bone showed less damage in the tumor-bearing NRP2-knockout mice compared to their control counterparts mainly due to less tumor growth and thus less tumor-induced osteolysis." (PMID 33990538, 2021). "Invalidation of NRP1 or NRP2 in RENCA cells delayed tumor incidence (percentage of mice with a tumor) as compared to the control group, in nude mice." (PMID 33461580, 2021). "To address this, we studied the role of NRP2 in PCa-induced osteoclasts and the effect of NRP2 inhibition on tumor growth." (PMID 33990538, 2021). "As reported by a previous work that M2 macrophage polarization is associated with the hypoxia TME and thus promotes tumor growth, we further uncover the specific molecules involved in these processes, including NRP1/NRP2 and LAMP1 expressed on TAMs." (PMID 34676217, 2021). "TAM-derived neuropilin-2 (NRP2) stimulates tumor growth by regulating efferocytosis of apoptotic tumor cells and coordinating immune suppression." (PMID 34722637, 2021). "Immunofluorescence studies on the bone tissues showed that the proliferation marker Ki67 was lower in the tumor cells of the NRP2-knockout mice than in the control mice." (PMID 33990538, 2021). "Since, osteoclasts present in the tumor microenvironment express NRP2, we have investigated the potential effect of targeting NRP2 in osteoclasts." (PMID 33990538, 2021). "These very low levels in MDAMB231 and the more specific effects of NRPa-308 on NRP2, partly explained the results obtained on experimental tumor growth." (PMID 33461580, 2021). "To address this critical question, we used a syngenic mouse tumor model of PCa bone metastasis, where NRP2 was specifically deleted from osteoclasts." (PMID 33990538, 2021). "Nrp2 blockade reduces tumor lymph angiogenesis and VEGFC-induced lymphatic endothelial cell migration." (PMID 33712565, 2021). "The tumor promoter role of NRP2 in ESCC has been demonstrated in our previous study, and a positive correlation between RMRP and NRP2 was found in the present study." (PMID 34516335, 2021). "The expression of both NRP1 and NRP2 was found in many tumor types, where their overexpression contributed to metastasis." (PMID 35008571, 2021). "Taken together, these outcomes indicate that downregulation of NRP2 suppresses PNET angiogenesis and tumor growth in vivo and is associated with longer survival in humans." (PMID 32983407, 2020). "In a different study, NRP2 signaling exhibited enhanced tumor initiation via stimulation of the α6β1 integrin and FAK-mediated Ras/MEK signaling." (PMID 33396906, 2020). "Among the differentially regulated miRNA–mRNAs axes, we focus on the miR-146a-Neuropilin2 (NRP2) axis, which is known to influence tumor aggressiveness." (PMID 33396906, 2020). "The intercellular interaction between integrins α5β1 and α9β1 expressed on endothelial cells and NRP2 expressed on tumor and endothelial cells increases tumor spreading and metastasis through and integrin-dependent mechanism." (PMID 32766254, 2020). "Among the tumor specimens with IDH mutation, mRNA levels of SEMA3B, SEMA3C, SEMA3D, SEMA3G, NRP2, PLXNA2, and CDH1 were significantly higher (p < 0.05), while SEMA3F, NRP1, ITGB3, ITGA5, and VEGFA genes were under-expressed (p < 0.05)." (PMID 33036421, 2020). "This subpopulation differentially expresses genes that have been shown to be tissue-reparative (Hmox1, Gas6) and tumor-promoting (Pf4, Fgfr1, and Nrp2)." (PMID 33072601, 2020). "SEMA3C, which binds to NRP1 and NRP2 with equivalent affinity, inhibits tumor lymphangiogenesis by targeting immature vessels sprouting." (PMID 32766254, 2020). "By targeting NRP-2, tumor growth and lymphangiogenesis were significantly suppressed in colorectal carcinoma in a nude mouse model." (PMID 33172072, 2020).